KDM4F (lysine demethylase 4F)
Description:
Probable histone demethylase that specifically demethylates 'Lys-9' of histone H3, thereby playing a central role in histone code.
Synonyms: JMJD2F
Gene: Protein-coding gene on chromosome 11 (95,048,142 to 95,051,338, forward strand). Ensembl gene ENSG00000255855.
Subcellular location: Nucleus
Gene Ontology:
Molecular function: histone H3K9 demethylase activity; histone H3K9me2/H3K9me3 demethylase activity
Biological process: chromatin remodeling
Cellular component: chromatin; nucleus
Genetic constraint (gnomAD): Missense variants: 270 observed, 261.08 expected, observed/expected ratio (o/e) 1.03, 90% interval 0.94 to 1.14. Synonymous variants: 95 observed, 98.97 expected, observed/expected ratio (o/e) 0.96, 90% interval 0.81 to 1.14.
Homologues: Orthologues: chimpanzee KDM4F (97% identical), macaque KDM4F (88% identical), zebrafish kdm4c (39% identical), Drosophila melanogaster Kdm5 (20% identical), Caenorhabditis elegans rbr-2 (17% identical). Paralogues in human: KDM4E (66% identical), KDM4D (56% identical), KDM4B (45% identical), KDM4C (41% identical), KDM4A (40% identical), KDM5A (21% identical), KDM5B (21% identical), KDM5C (20% identical), KDM5D (20% identical), JARID2 (15% identical).
Diseases named in the same sentence as KDM4F in open-access papers:
KDM4F is named in the same sentence as 1 disease in open-access papers, as found by Europe PMC text mining. Sharing a sentence is not in itself a finding about the gene and the disease.
KDM4F shares sentences with these, for which no sentence is quoted: cancer (1 paper).